BRAF (B-Raf proto-oncogene, serine/threonine kinase)
Diseases named in the same sentence as BRAF in open-access papers (continued):
Sharing a sentence is not in itself a finding about the gene and the disease.
tumor (continued). "It will be interesting to see if further optimization of the peptides is possible by using additional modes of delivery, altered sequences or longer stretches of the peptide and whether these are applicable against BRAF/inhibitor-resistant tumor from patients." (PMID 26279295, 2016). "We also observed mutations in HRAS at codons 61 and 12 (two and one samples, respectively), and a single BRAF V600E mutation in an ER− tumour, although the two genes did not meet Mut-driver criteria." (PMID 27161491, 2016). "All of these genes have been associated with tumor growth and progression, and recent studies suggest that additional mutations in KRAS and NRAS, as well as downstream mutations in BRAF or PIK3CA, may cause resistance to anti-EGFR treatment." (PMID 26989027, 2016). "In addition, AMPK activation seems to have both anti-tumor and pro-tumor effects in melanoma cells expressing the oncogene BRAF." (PMID 26918349, 2016). "Importantly, RLH activation suppressed all of these responses and increased LIMK2, p-cofilin and the PTEN tumor suppressor gene while decreasing the expression of BRAF." (PMID 27198666, 2016). "Tumors from animals treated with PD-L1 blockade or PLX4720 alone had visibly higher infiltration of CD8+ T cells compared to controls; in the tumors treated with the BRAF inhibitor most of the T cells appeared to have infiltrated into the peripheral aspects of the tumor." (PMID 26943572, 2016). "BRAF fusion events were exclusively seen in low grade tumours, were never associated with H3K27M and were associated with excellent long-term survival (5+ year survival of 78.6 % [11/14])." (PMID 27577993, 2016). "Moreover, in a patient who shows a significant response to BRAF inhibitors, BRAF-driven cells must be dominating the tumor(s) at the time of treatment when the drug affects the majority of cells." (PMID 26977879, 2016). "While KRAS mutations were frequently detected in 46 (41%) out of 112 FAP tumor samples, no sample was BRAF-mutation(+)." (PMID 27563825, 2016). "Since suboptimal suppression of ERK activity might permit tumor growth in BRAF mutant cancers, we determined the cellular effects of drug response when lowering drug concentrations." (PMID 27845624, 2016). "No other significant associations were found for either MSS or MSI-H cases between ITF2 methylation and early age of onset (<50 years), stage, grade, tumor location, histological type, MMR protein status, MMR germline mutation, BRAF V600E mutation, or survival status." (PMID 26884349, 2016). "Considering that no BRAF-mutation was detected, it suggested that high-methylation epigenotype with BRAF mutation is not involved in tumorigenesis of FAP tumor." (PMID 27563825, 2016). "Finally we provide clinical arguments suggesting that an important fraction of BRAF V600mut ctDNA correlates with the BRAF V600mut-dependent proliferative tumor burden." (PMID 27095081, 2016). "In fact, BRAF inhibitors treatment is associated with decreased production of the immunosuppressive factor IL10 and enhanced expression of tumor-specific antigens and so BRAF inhibitors might induce T-cell infiltration before treatment with immunotherapy." (PMID 26863566, 2016). "These included specific types of somatic mutations (e.g. BRAF), germline mutations (e.g. BRCA1), biomarkers (e.g. CA125), risk factors (e.g. UV exposure) prognostic features of the tumor (e.g. tumor infiltrating lymphocytes), and specific clinical features (e.g. associated ascites)." (PMID 27629872, 2016). "A recent report of systematic review and meta-analysis of 21 studies indicated high-risk clinicopathologic characteristics in colorectal tumors with BRAF mutations in terms of TMN stage (T4 tumors), differentiation (poor differentiation), and tumor location (proximal location)." (PMID 27127793, 2016).
tumor (continued). "In general, higher metabolic activity is related to increased tumor aggressiveness, and higher expression levels of proteins related to serine/glycine metabolism might be expected in BRAF V600E-positive cases." (PMID 27277113, 2016). "BRAF D594N is a kinase-dead protein; nevertheless, considering results in mice co-occurrence of BRAF D594N and KRAS mutations might contribute to tumor progression." (PMID 27095580, 2016). "The association between BM and mutation in PIK3CA and BRAF, expression of NCAM, EGFR, and CXCR4, MGMT methylation and increase in the tumor marker CA19.9 have also been investigated, but only in one or two studies each and on small samples, so the possible predictive potential is hard to determine." (PMID 27037031, 2016). "Conversely, a number of recent studies suggest that tumors are heterogeneous for the BRAF mutation and that not every cell in a BRAF mutation-positive tumor has a heterozygous mutation." (PMID 27410688, 2016). "Moreover, we explored the biological meaning of BRAF immunohistochemical labeling both as a predictor marker of response to target therapy and, for the first time, as a player of acquired tumor drug resistance." (PMID 27863476, 2016). "In addition, ∼20% of patients show primary/intrinsic resistance to BRAF inhibitors and experience tumor progression at first assessment during therapy." (PMID 26678033, 2016). "Melan-A cells, normal immortalized mouse melanocytes, showed increased cellular proliferation upon introduction of exogenous mutated BRAF (V600E), however no tumor formed." (PMID 27941674, 2016). "Patients with sporadic MSI CRC are older and the tumours are characterised by frequent BRAF (V600E) mutation and absence of MLH1 and PMS2 proteins." (PMID 27340376, 2016). "Interestingly, acute ERK1/2 hyper-activation in tumors by the oncogenic BRAF[V600E] mutant leads to tumor cell senescence." (PMID 27303665, 2016). "VEM would have been predicted to be active against this tumor, which has a BRAF- V600E-mutation which VEM targets, but VEM was not effective." (PMID 27690220, 2016). "A higher BRAF mRNA expression level was associated with tumor aggressiveness in classic PTC regardless of BRAF mutational status." (PMID 27410688, 2016). "Recently we also showed that in an in vivo mouse model with conditioned mutated BRAF (V600E), GRM1 expression is detected after mutated BRAF expression is activated, however, no tumor was detected in these mice up to 17 months of age." (PMID 27941674, 2016). "In either case, the molecular test report would not accurately reflect whole picture of the BRAF gene mutation status, again emphasizing the necessity to microdissect each tumor nodule/component separately for mutation testing." (PMID 27597976, 2016). "In fact, the additional activating mutation in NRASQ61K found in patient 1 with a BRAF mutation background was only present in a single metastasis of patient 1 and absent in all other resistant tumor samples from that patient." (PMID 27791198, 2016). "Indeed, concurrent inhibition of BRAF and PIK3CA/mTOR induced tumor regression in a BRAF-mutant CRC mouse model." (PMID 26299805, 2015). "Although PI-88 is an investigational drug not currently approved by the FDA, we show here evidence that it may support inhibition of tumor angiogenesis in combination with other BRAF inhibitors." (PMID 26262134, 2015). "Interestingly, one tumor sample harbored two different KRAS mutations (p.G13D and p.Q61R) whilst another tumor was KRAS/BRAF double mutant." (PMID 25568935, 2015). "Additionally, a mouse anti-human BRAF monoclonal antibody was tested on 30 FFPE tumor samples with known BRAF status." (PMID 25983749, 2015). "Importantly, residual tumor masses from mice treated by the antibodies and BRAF/ERK inhibitors combo are characterized almost exclusively by large necrotic areas with limited residual areas of tumor growth." (PMID 26208478, 2015).
tumor (continued). "BRAF inhibition has been shown to increase immune reaction in the tumor microenvironment." (PMID 26152183, 2015). "These events may include mutations in key genes that when estimated as % of the tumor population emerge as subclonal events in different MM patients: KRAS (20–72%), NRAS (32–96%), BRAF (36–92%) or DIS3 genes (29–81%)." (PMID 25929340, 2015). "This suggests that combining BRAF-targeted therapy with IL-2 could contribute to increased tumor destruction." (PMID 25709607, 2015). "However, clinical studies on patients have shown that although BRAFi (BRAF inhibitors) trigger early anti-tumor responses, the majority of patients later develop resistance to the therapy." (PMID 26393652, 2015). "In vitro testing indicated that sorafenib may lead to paradoxical ERK activation in both wild-type BRAF and fusion KIAA1549:BRAF tumor cells as well as NF1-deficient cells, suggesting that BRAF inhibitors should only be used in BRAFV600E-mutant tumors." (PMID 26525348, 2015). "That biopsy, which no longer showed the BRAF mutation, was obtained from a tumor that was enlarging; other tumors that had shown the BRAF mutation were regressing on BRAF-targeted therapy." (PMID 25886620, 2015). "It has been reported that some cell types in the tumor microenvironment such as stromal cells can secrete growth factors like hepatocyte growth factor (HGF) or tumor necrosis factor-α (TNF-α) resulting in resistance to BRAF inhibition." (PMID 25939769, 2015). "Concordance of plasma and tumor results for RAS and BRAF mutations." (PMID 25954997, 2015). "BRAF mutant allele frequencies were highly concordant with the KRAS and NRAS mutant allele frequencies, suggesting that concomitant mutations are present in the same tumor population." (PMID 26498038, 2015). "PCC/PGLs with BRAF V600E mutations may be predicted to respond to BRAF and MEK inhibitors, such as vemurafenib and trametinib/selumetinib, better than wild type BRAF tumours." (PMID 25883647, 2015). "The patient’s brain metastasis was a BRAF V600E mutated, NRAS WT, TERT C250T mutated tumor with evidence of germline SNPs that may be associated with improved OS." (PMID 26597176, 2015). "Taken as a whole, these observations support the notion that TRAP1 quality control and antiapoptotic protein network is a potential molecular target for anticancer therapy and that BRAF-addicted tumors are a suitable and attractive tumor cell model to evaluate this novel therapeutic strategy." (PMID 26084290, 2015). "However, truncated and fusion RAF1 and BRAF transcripts have been found to occur in several cancer cell lines and tumor samples." (PMID 25473895, 2015). "Moreover, about 20–30% patients develop squamous cell carcinoma and more develop tumor recurrence limiting vemurafenib therapy as well as other BRAF targeted therapies." (PMID 26497853, 2015). "Since we observed high expression of MGL ligands in cells harboring activating mutations in BRAF, we next assessed whether interference with BRAFV600E and the downstream MAPK pathway would revert expression of MGL ligands on the tumor cell surface." (PMID 26172302, 2015). "Importantly, the PIK3CA mutations and BRAF mutations, occurring in cases with wild-type KRAS, are known to be mechanistically activating and are enriched in other tumour types." (PMID 25855536, 2015). "In addition, testing of cfDNA demonstrated acceptable concordance (BRAF, 91%; EGFR, 99%; KRAS, 83%; PIK3CA, 91%) with standard of care mutation analysis of primary or metastatic tumor tissue obtained during clinical care." (PMID 25980577, 2015). "The difference of the histological variants repartition in the BRAF V600E negative and positive tumor populations was assessed by a two-side Fisher’s exact test which was very significant: pval < 0.0001." (PMID 26487287, 2015).
tumor (continued). "In summary, we here propose a model in which activating BRAF mutations, and possibly other oncogenic alterations that activate the MAPK pathway, lead to an altered tumor cell glycosylation profile and enhanced expression of MGL ligands, presumably the Tn antigen." (PMID 26172302, 2015). "The induction of RHOB after MAPK pathway inhibition suggests that this phenomenon could be a common feature for BRAF-mutant tumor cells." (PMID 26098773, 2015). "However, the macrophage inhibitory effects of PLX3397 treatment in combination with the paradoxical activation of wild type BRAF-expressing immune cells mediated by PLX4032 resulted in more tumor-infiltrating lymphocytes (TIL)." (PMID 25939769, 2015). "BRAF mutant tumours may attain part of their chemoresistance from abnormal TFAP2E methylation, which has not previously been described." (PMID 26097884, 2015). "Further study is needed in a larger cohort to identify the potential of these identified changes, and also to fully understand the mechanisms that lead to BRAF tumours becoming chemoresistant and having a poorer prognosis, as this is unlikely to be due to a single pathway phenomenon." (PMID 26097884, 2015). "Tumours with average DNA copy number <2.5 frequently exhibited MSI and mutated BRAF." (PMID 25884297, 2015). "Three of them (HOXA11, MET, BRAF) are potential oncogenes currently being observed for common copy-number gains in a meta-analysis of copy number alterations across a panel of different cancer cell lines and tumor samples." (PMID 26043758, 2015). "Whereas BRAF and MEK targeted agents specifically inhibit a node in the MAPK signaling pathway that can eventually be overcome by tumor mutation, cancer immunotherapy has the potential to induce the inherent capacity of the immune system to adapt to mutational tumor changes." (PMID 25682878, 2015). "Among the 10 cases of discordant BRAF V600E genotypes, it is difficult to conclude whether this discordance is due to possible contaminations, tumor heterogeneity or to other factors such as DNA quality or preanalytical parameters." (PMID 25789737, 2015). "BRAF mutations were associated with lower likelihood of tumour dissemination in the whole cohort, as well as lower likelihood of metastatic recurrence in a separate analysis of stage II and III tumours." (PMID 25884297, 2015). "In addition, we performed multivariate Cox regression combining MACC1 expression level with the tumor characteristics KRAS G12 or G13 mutation, BRAF V600 mutation and MSI status." (PMID 25742883, 2015). "Inclusion of other risk factors in the model (age, sex, the degree of tumor infiltrating lymphocytes, BRAF/NRAS mutation status and tumor regression) did not result in an increase of the AUC." (PMID 25871393, 2015). "A possible explanation is that such mutations are preexisting in patients only in a minor tumor subclone that no longer relies on oncogenic BRAF signaling." (PMID 26481584, 2015). "The MiSeq analysis also revealed that the two low-tumor-cellularity samples in which Idylla but not cobas had identified a BRAF mutation contained 4.6% V600E and 5.7% V600R, respectively, which is in line with the overall specifications of the cobas test." (PMID 26330075, 2015). "A number of studies have revealed the ‘RAF inhibitor paradox' in which CRAF is activated and tumour growth enhanced for tumours with activating mutations in KRAS but not BRAF." (PMID 26333361, 2015). "The initial biopsy did not contain any viable tumour cells when examined by pathologists, and hence no mutation testing was done on the sample, rendering the patient ineligible for BRAF inhibitor based therapies." (PMID 26095797, 2015). "While multiple AAHs or MIA tumours may share common alterations (such as BRAF or EGFR, respectively), specific mutations are limited to individual patients in relatively more heterogeneous AIS tumours." (PMID 26374070, 2015). "One patient showing partial response to SL/Bev had a BRAF-mutant tumor." (PMID 26311588, 2015).
tumor (continued). "In three of these 12 cases (25%), discrete PTC foci showed a discordant BRAF mutational status: in case 3, tumor A had the BRAF mutation, while tumors B and C did not; in cases 6 and 12, tumor A lacked the BRAF mutation, whereas tumor B displayed it." (PMID 25882744, 2015). "Furthermore, the resistance-conferring BRAF amplification was heterogeneous even within a single metastasis, suggesting that multiple resistance mechanisms can be present within a single tumor." (PMID 26105199, 2015). "We hypothesize that this set of mutations in growth pathways and tumor suppressors potentially explains SKMEL28’s resistance to PLX4720 treatment, despite its homozygous BRAF status." (PMID 26405815, 2015). "Nevertheless, the clinical results with BRAF inhibitors in CRC tumours have been quite deceptive." (PMID 25932044, 2015). "Therefore, if only the largest tumor is tested, a substantial number of patients would be considered BRAF-negative even though they harbor a smaller tumor that is BRAF-positive." (PMID 26448939, 2015). "Further in vivo studies confirmed the role of mutated BRAF in PTC progression through genes related to tumor invasion and metastasis and demonstrated the key role of TSH signaling in BRAF-induced PTC initiation and its relation to more aggressive features of BRAF(+) PTCs." (PMID 26625260, 2015). "Two patients with a BRAF mutation in the primary tumor did not carry a mutant allele in their CTC subpopulation." (PMID 25902072, 2015). "RAS and several of its downstream effectors, including BRAF, have been shown to be commonly mutated in a broad range of human cancers and biological studies have confirmed that RAS pathway activation promotes tumour initiation, progression and metastatic spread in many contexts." (PMID 25361007, 2014). "Given that tumor BRAF V600E mutation has been widely advocated as a negative predictor for LS-associated CRCs, there is a high likelihood that these two cases are likely sporadic CRCs or arise from hypermethylation pathways." (PMID 24710284, 2014). "Mutations in KRAS and BRAF are mutually exclusive, but KRAS and PIK3CA mutations may coexist within the same tumor." (PMID 25361007, 2014). "BRAF inhibition has been shown to have significant anti-tumor efficacy in BRAFV600E mutant cancers." (PMID 25222836, 2014). "The median ages of patients whose tumor tissue contained mutations of KRAS, PIK3CA and NRAS (54.5, 58.0 and 56.0 years, respectively) were lower than that of patients containing all-wild types of KRAS, BRAF, PIK3CA and NRAS (median age, 64.0 years)." (PMID 24774510, 2014). "Twenty-six patients (9.12%) with tumor < 1 cm and without risk factor (lymph node involvement, extra-capsular invasion, unfavorable histological subtype, multifocal disease, or BRAF-positive) were not submitted to adjuvant radioiodine ablation." (PMID 24885654, 2014). "Moreover, early adaptive responses limit the initial efficacy of BRAF inhibition, leading mostly to incomplete responses that may favor the selection of a sub-population of resistant clones and the acquisition of alterations that cause tumor regrowth and progressive disease." (PMID 25344914, 2014). "The BRAFV600E mutation suggests that ERK, a downstream effector of BRAF, may play a major role in the carcinogenesis of PTC, and is associated with extrathyroid invasion, lymph node metastases, advanced tumor stage, and frequent recurrence." (PMID 25329702, 2014). "The BRAF mutation was found in both tumor areas in all cases, suggesting a common origin for the components, rather than a collision tumor." (PMID 24321241, 2014). "Nevertheless, to assess the clinical usefulness of our platform, we randomized nine mice carrying this patient’s tumor into three treatment groups receiving vemurafenib (BRAF inhibitor), trametinib (MEK inhibitor) or a combination, mimicking the clinical trial design." (PMID 25228592, 2014).